ATP6V0D2 (ATPase H+ transporting V0 subunit d2)
Description:
Subunit of the V0 complex of vacuolar(H+)-ATPase (V-ATPase), a multisubunit enzyme composed of a peripheral complex (V1) that hydrolyzes ATP and a membrane integral complex (V0) that translocates protons. V-ATPase is responsible for acidifying and maintaining the pH of intracellular compartments and in some cell types, is targeted to the plasma membrane, where it is responsible for acidifying the extracellular environment (By similarity). May play a role in coupling of proton transport and ATP hydrolysis (By similarity). Regulator of osteoclast fusion and bone formation (By similarity).
Synonyms: FLJ38708; VMA6; ATP6D2
Tractability: Antibody: its Gene Ontology location is reachable by antibodies, with medium confidence.
Gene: Protein-coding gene on chromosome 8 (85,987,323 to 86,154,227, forward strand). Ensembl gene ENSG00000147614.
Subcellular location (Human Protein Atlas): Vesicles
Pathways (Reactome):
Transport of small molecules: Ion channel transport; Transferrin endocytosis and recycling
Cellular responses to stimuli: Amino acids regulate mTORC1
Immune System: ROS and RNS production in phagocytes
Signal Transduction: Insulin receptor recycling
Gene Ontology:
Molecular function: protein binding; proton-transporting ATPase activity, rotational mechanism
Biological process: regulation of macroautophagy; vacuolar acidification; vacuolar transport; proton transmembrane transport
Cellular component: apical plasma membrane; extracellular exosome; membrane; vacuolar proton-transporting V-type ATPase complex; early endosome; endosome membrane; lysosomal membrane; phagocytic vesicle membrane; plasma membrane proton-transporting V-type ATPase complex; endosome; proton-transporting V-type ATPase, V0 domain
Genetic constraint (gnomAD): Loss-of-function variants: 30 observed, 29.69 expected, observed/expected ratio (o/e) 1.01, 90% interval 0.75 to 1.37. The upper end of that interval is the gene's LOEUF score, 1.37, which puts it in group 5 of 6, group 1 being the genes least tolerant of losing a copy. Missense variants: 363 observed, 345.5 expected, observed/expected ratio (o/e) 1.05, 90% interval 0.96 to 1.15. Synonymous variants: 138 observed, 131.03 expected, observed/expected ratio (o/e) 1.05, 90% interval 0.92 to 1.21.
Homologues: Orthologues: chimpanzee ATP6V0D2 (100% identical), macaque ATP6V0D2 (99% identical), dog ATP6V0D2 (95% identical), pig ATP6V0D2 (94% identical), rabbit ATP6V0D2 (94% identical), mouse Atp6v0d2 (93% identical), rat Atp6v0d2 (92% identical), guinea pig ATP6V0D2 (91% identical), Caenorhabditis elegans vha-16 (61% identical), tropical clawed frog atp6v0d2 (60% identical). Paralogues in human: ATP6V0D1 (68% identical).
Diseases named in the same sentence as ATP6V0D2 in open-access papers:
ATP6V0D2 is named in the same sentence as 34 diseases in open-access papers, as found by Europe PMC text mining. Sharing a sentence is not in itself a finding about the gene and the disease. The quoted sentences say what the papers report.
atherosclerosis (2 papers, 2019 to 2022). A disease characterized by the build-up of fatty material and calcium deposition in the arterial wall resulting in partial or complete occlusion of the arterial lumen. "In summary, our results support the conclusion that these proteins (i.e., SPP1, ATP6V0D2, CHI3L1, and BDNF) likely play important roles in the development of atherosclerosis-related diseases and further indicate that they are potential diagnostic and therapeutic biomarkers." (PMID 31682178, 2019). "Furthermore, our study indicates that SPP1, CD36, ATP6V0D2, CHI3L1, MYH11, and BDNF, which showed favorable diagnostic performance and high correlations with several clinical biochemical parameters, may potentially serve as biomarkers to diagnose and monitor the prognosis of atherosclerosis." (PMID 31682178, 2019).
esophageal cancer (2 papers, 2021 to 2024). A primary or metastatic malignant neoplasm involving the esophagus. "Previous research has established that ATP6V0D2 is intricately linked to alterations in the extracellular matrix and plays a role in fostering esophageal cancer invasion and metastasis by modulating the epithelial-mesenchymal transition (EMT) pathway." (PMID 39678496, 2024). "ATP6V0D2 has also been found to influence the development and progression of esophageal cancer and lung adenocarcinoma and is associated with the prognosis of patients." (PMID 39678496, 2024). "Furthermore, ATP6V0D2 was markedly upregulated in esophageal cancer, where it was associated with enhanced proliferative and metastatic abilities of esophageal cancer cells." (PMID 39678496, 2024). "ATP6V0D2 is a subunit related to proton transport, which plays a carcinogenic effect in esophageal cancer and is related to epithelial–mesenchymal transition." (PMID 34124063, 2021). "Results indicated significantly overexpression of ATP6V0D2 in BRCA, bladder urothelial carcinoma (BLCA), esophageal carcinoma (ESCA), cholangiocarcinoma (CHOL), stomach adenocarcinoma (STAD), and several other types of cancer compared to normal tissues." (PMID 39678496, 2024).
gastric cancer (2 papers, 2020 to 2024). A primary or metastatic malignant neoplasm involving the stomach. "ATP6V0D2 also exhibited elevated expression in gastric cancer, whereas it was significantly downregulated in colon cancer." (PMID 39678496, 2024). "Previous studies showed that an elevated expression of ATP6V0D2 was found in stomach cancer specimens, whereas the expression was reduced in the colorectal and renal cancer specimens, which confirmed our findings." (PMID 32002016, 2020).
Obesity (2 papers, 2025). Accumulation of substantial excess body fat. "Moreover, genes involved in lysosomal biogenesis and phagocytosis including Atp6v1b2, Atp6v0d2, Lipa, and Lamp2 were also reported to be induced in the ATMs in obesity." (PMID 40244655, 2025).
asthma (1 paper, 2024). "ATP6V0d2, a subunit of ATP6V0D2 that is abundantly expressed in macrophages, has been demonstrated to operate as an induced feedback inhibitor of asthma disease severity by boosting Pu.1 lysosomal degradation, which may contribute to the polarization of activated macrophages." (PMID 38660308, 2024).
breast carcinoma (1 paper, 2024). "ATP6V0D2 is also likely to enhance the proliferation and metastatic potential of breast cancer cells through the activation of the TGF and FAK signaling pathway or by preventing the deactivation of those pathways." (PMID 39678496, 2024). "The analysis of IHC staining score also revealed a marked increase in the expression levels of the ATP6V0D2 protein within the breast cancer tissue samples." (PMID 39678496, 2024). "ATP6V0D2 acts as a promising indicator for both diagnosis and prediction of outcomes in breast cancer and could potentially be a novel therapeutic target for BRCA." (PMID 39678496, 2024). "Targeting ATP6V0D2 could potentially suppress the activity of these pathways, thereby inhibiting the progression of breast cancer." (PMID 39678496, 2024). "Consequently, the combined targeting of ATP6V0D2 with immunosuppressive agents could potentially enhance the potency of immunotherapy, thereby extending its benefits to a broader range of patients with advanced breast cancer, especially TNBC patients." (PMID 39678496, 2024).
cardiomyopathy (1 paper, 2025). A disease of the heart muscle or myocardium proper. "Downregulated proteins in the aged group (TUBGCP2 and SLC25A11) were enriched in cytoskeletal dynamics and cardiomyopathy pathways, whereas upregulated proteins (ATP6V0D2 and TPM1) associated with oxidative stress and neurodegenerative disorders." (PMID 40662159, 2025). "Prominently downregulated proteins (TUBGCP2, NPR2, MT-ATP6, SLC25A11, and so on) were enriched in cytoskeletal dynamics and cardiomyopathy pathways, while upregulated proteins (ATP6V0D2, HNRNPA1, TPM1, and so on) associated with oxidative stress responses and neurodegenerative disorders (AD and PD)." (PMID 40662159, 2025).
colon adenocarcinoma (1 paper, 2024). "In contrast, prostate adenocarcinoma (PRAD), kidney renal clear cell carcinoma (KIRC), lung adenocarcinoma (LUAD), and colon adenocarcinoma (COAD) exhibited significantly reduced ATP6V0D2 expression compared to normal tissues." (PMID 39678496, 2024).
coronary heart disease (1 paper, 2019). "We also performed ELISA to investigate the corresponding proteins levels of selected genes and showed that serum levels of SPP1, CD36, ATP6V0D2, CHI3L1, MYH11, and BDNF were differentially expressed in patients with coronary heart disease compared with healthy subjects." (PMID 31682178, 2019).
kidney cancer (1 paper, 2023). Primary or metastatic malignant neoplasm involving the kidney. "Previous studies also supported our result that ATP6V0D1 was widely expressed, while D2 was mainly expressed on the cell surface of human kidneys and osteoclasts; ATP6V0D2 is also overexpressed in most cancer tissues such as in melanoma, pancreatic cancer, and kidney cancer." (PMID 36980869, 2023).
myocarditis (1 paper, 2022). Myocarditis is a condition that is characterized by inflammation of the heart muscle (myocardium). "In this study, we identified 51 DEGs were upregulated in the myocarditis group compared with the control group, and the top three DEGs with the largest fold change were Mmp12, Gpnmb, and Atp6v0d2." (PMID 36226312, 2022).
oncocytomas (1 paper, 2023). "Importantly, sporadic ChRCCs and sporadic oncocytomas were further clustered into two distinct clusters, and differentially expressed genes (DEGs) analysis identified L1CAM, FOXI1 and its downstream gene, ATP6V0D2 as molecular markers for these distinct clusters (Group1 and 2)." (PMID 37182269, 2023).
parasite infection (1 paper, 2022). "Therefore, elucidation of the mechanisms for Leishmania-induced upregulation of ATP6V0D2 may lead to the control of parasite infection." (PMID 36211967, 2022).
peritonitis (1 paper, 2021). Inflammation of the peritoneum (tissue that lines the abdominal wall and covers most of the organs in the abdomen). "It has been proved that knockdown of ATP6V0D2 leads to enhanced inflammasome activation in BMDMs and in LPS-induced peritonitis." (PMID 33860063, 2021).
Salmonella Infections (1 paper, 2022). Infections with bacteria of the genus SALMONELLA. "ATP6V0D2 is involved in inflammasome activation, and its defect results in susceptibility to Salmonella infection." (PMID 36211967, 2022).
tumor (14 papers, 2020 to 2025). "These two populations expressed genes Cxcl3, Ccl3, Ccl4, Atp6v1c1, Atp6v0d2, which have been associated with a tumor promoting phenotype." (PMID 38265267, 2024). "Studies show that V-ATPase V0 subunit d2 (ATP6V0d2) expressed by macrophages inhibits tumor growth in vivo, while tumor-derived lactate inhibits ATP6V0d2 in macrophages, thereby promoting HIF-2α-mediated tumor progression." (PMID 40786181, 2025). "Affecting by key signaling pathways and molecules, ATP6V0D2 can regulate the polarization of macrophage as well as inflammatory cell infiltration, thereby affecting tumor progression and immune responses." (PMID 39678496, 2024). "In a pan-tumor tissue microarray, ATP6V0D2 was overexpressed in various kinds of carcinomas, including kidney cancer, pancreas cancers and melanoma." (PMID 39678496, 2024). "Collectively, these findings provide compelling evidence that silencing ATP6V0D2 inhibits TNBC tumor growth in vivo." (PMID 39678496, 2024). "The results indicated that ATP6V0D2 promotes proliferation, migration, and invasion abilities of TNBC cells, furthermore we verified ATP6V0D2 promotes tumor growth in vivo experiments, suggesting the function of ATP6V0D2 as an oncogene." (PMID 39678496, 2024). "Lactic acid induces the activation of mTORC1 in macrophages, thereby inhibiting the expression of ATP6V0D2 in tumor-associated macrophages and promoting HIF-2α-mediated tumor progression." (PMID 33860063, 2021). "Downregulated ATP6V0D2 probably functions through increasing HIF-2α expression produced by macrophage to enhance tumor vascularization and growth." (PMID 32002016, 2020). "Furthermore, ATP6V0D2 plays an important role in immune cells, especially in the functional regulation of macrophages, the tumor microenvironment, and the innate immune response." (PMID 39678496, 2024). "However, a contrary finding showed that blocking selective lysosomal degradation by ATPase H+ transporting V0 subunit d2 (ATP6V0d2) knockout elevated M2-like markers in TAMs resulting in promoted tumor growth in tumor-bearing mice." (PMID 33990205, 2021). "The inhibition of ATP6V0d2 could mediate HIF-2α lysosomal degradation and program TAMs (tumor-associated macrophages) in the tumor microenvironment into immune cells that promote tumor growth." (PMID 33546704, 2021). "Among the five genes in ccRCC, ATP6V0D2, DPP6, PADI1 and PLG were significantly associated with AJCC-stage (p < 0.05); ATP6V0D2, C9orf135, DPP6 and PLG were significantly associated with nodal metastasis (p < 0.05); ATP6V0D2, DPP6 and PLG were significantly associated with tumor grade (p < 0.05)." (PMID 32002016, 2020). "But the specific correlation of ATP6V0D2 dysregulation and tumor acidity remains uncertain." (PMID 32002016, 2020).
cancer (3 papers, 2014 to 2024). A tumor composed of atypical neoplastic, often pleomorphic cells that invade other tissues. "ATP6V0D2 has also been linked to the development of a range of cancers." (PMID 39678496, 2024). "ATP6V0D2 exhibited high expression in a range of cancers and correlated with unfavorable prognosis in BRCA." (PMID 39678496, 2024). "This analysis revealed that ATP6V0D2 expression levels were markedly aberrant in the most types of cancers." (PMID 39678496, 2024). "Researches have identified ATPase H+ transporting V0 subunit d2 (ATP6V0D2) as a significant factor in various cancers." (PMID 39678496, 2024). "In the present study, we found significant upregulation of ATP6V0D2 in nine out of 21 human cancer tissues, including BRCA from TCGA and GEO datasets." (PMID 39678496, 2024). "This study investigated ATP6V0D2 expression across various cancers and assessed its prognostic significance in BRCA, along with its potential diagnostic implications." (PMID 39678496, 2024). "The most up-regulated genes in U87 cells were interleukins and receptors (IL1A, IL13RA2, IL1RN), CT45A5 from the cancer/testis (CT) family of antigens, and the cytoplasmic transporter ATP6V0D2." (PMID 25481245, 2014).
infection (3 papers, 2020 to 2024). The state of being infected such as from the introduction of a foreign agent such as serum, vaccine, antigenic substance or organism. "Staphylococcus aureus is the common causative organism in osteomyelitis, and its infection in macrophages induces upregulation of ATP6V0D2 expression and acquisition of osteoclast-like bone resorption activity." (PMID 38357442, 2024). "Although ATP6V0D2 is a demonstrated factor inducing the formation of hemophagocytic MGCs during L. donovani infection, functions of this protein in shaping the infection outcome in macrophages remain unclear." (PMID 38357442, 2024). "Infection-induced ATP6V0D2 localized in a cytoplasmic compartment, which did not overlap with the mitochondria, endoplasmic reticulum, or lysosomes." (PMID 36211967, 2022).
liver (1 paper, 2021). "Regardless, our work complements the mapping of the liver IR inflammatory activation mechanism, helping to further understand the role of ATP6V0D2 in the context of liver IR-induced innate immunity." (PMID 33860063, 2021). "ATP6V0D2 is undoubtedly involved in the regulation of the inflammation of liver IR." (PMID 33860063, 2021).
ATP6V0D2 also shares sentences with these, for which no sentence is quoted: osteoporosis (2 papers); cholangiocarcinoma (1); clear cell renal cell carcinoma (1); colon cancer (1); hepatic carcinoma (1); Insulin resistance (1); lung adenocarcinoma (1); melanoma (1); mesothelioma (1); ovarian carcinoma (1); pancreatic cancer (1); prostate adenocarcinoma (1); renal carcinoma (1); stomach adenocarcinoma (1); stomach cancer (1).